IL2 (interleukin 2)
Diseases named in the same sentence as IL2 in open-access papers (continued):
Sharing a sentence is not in itself a finding about the gene and the disease.
COVID-19 (continued). "Interestingly, in this study, the analysis of the differential expression of cytokines in the mild and severe COVID-19 patient groups revealed the expression of IL-2, IL-6, TNF-α, and IFN-γ to be significantly decreased in severe cases as compared to mild cases." (PMID 36584119, 2022). "Both single-cell immune response (endogenous signaling and signaling response to IFNα/IL-2/IL-4/IL-6 and LPS/CL097; factor 10) and plasma proteome (factor 3) data contributed strongly to the variance observed in our samples and were significantly associated with COVID-19 severity." (PMID 35839768, 2022). "Conversely, low PD-1 synthesis and high IL-2 and IFN-gamma expression in helper and cytotoxic T cells and an increased IFN-alpha production in classical and non-classical monocyte subsets are related to a basal predisposition to developing mild COVID-19 symptoms after SARS-CoV-2 exposure." (PMID 35860236, 2022). "Therefore, a highlight in IL-2 appears to be crucial to immune surveillance against COVID-19." (PMID 36685603, 2022). "Hence, we could assume that IL-2 may be a factor in the adverse effects of aspirin in patients with aspirin after COVID-19, and further studies are needed to validate this." (PMID 34577854, 2021). "Other micronutrients as vitamin E, together with the minerals zinc and selenium, are known to improve recovery from influenza viral infection and may be of interest in COVID-19 treatment, as Vitamin E is involved in the dendritic cells, influence interleukin IL-2 production, and T-cell regulation." (PMID 34068930, 2021). "Additionally, TFH cells predominantly produce IL-2, IL-4 and IL-21 in B cell follicles and closely regulate antibody class-switching in severe inflammatory and allergic diseases, including AD, asthma, and COVID-19-induced airway inflammation." (PMID 34531749, 2021). "Thus, adipose IRF5 transcripts in obesity correlate positively with TNF-α, IL-1β, IL-6, CXCL8/IL-8, CXCL9/MIG, CXCL10/IP10, CCL2/MCP1, CCL5, and CCL7/MCP3, all of which can be elevated in COVID-19 “cytokine storm”; positive correlations with IL-2 and IL-12 have been reported by the same group." (PMID 33936053, 2021). "Moreover, gene expression analyses in the CD4+ T cells from COVID-19 patients revealed a decrease in IL-2 transcripts in severe COVID-19 cases compared to mild cases, which could be another reason for decreasing Treg cells." (PMID 35126355, 2021). "The present data indicate that DPSC administration might be effective in patients with COVID-19-induced hyper-inflammation, due to the inhibition in the production of several cytokines by activated T lymphocytes, namely, IFNγ, TNFα, IL-2, IL-9, IL-10, IL-17A, IL-18, IL-21, and IL-27." (PMID 33634100, 2020). "By recalling the same patients over up to 40 months, we were able to measure longitudinal serum antibody levels and IL-2 and IFN-γ over the years to assess if patients with long COVID show serological or cellular changes in immune function after COVID-19." (PMID 41324571, 2025). "At low exposure levels, COVID-19-positive individuals maintained consistent production of TNF, IL-2, IL-10, and IL-6, with multiple IFN-γ peaks." (PMID 40406109, 2025). "The analysis of cord blood samples at Early and Intermediate convalescent COVID-19 showed increased levels of CCL11, CCL3, CCL4, CCL2, IL-1β, IFN-γ, IL1-Ra, G-CSF, and IL-7 and a decrease of IL-10 and IL-2 as compared with HC." (PMID 40821818, 2025). "Few studies have examined the functional spike-specific CD4+ and CD8+ T cell responses by evaluating IFN-γ-, IL-2, or TNF-α-producing T cells by flow cytometry in PwMS after the third dose of COVID-19 mRNA-vaccines." (PMID 41246331, 2025). "Supervised machine learning algorithm (RF) was used to predict the COVID-19 severity and chronicity based on immune subset profiling and a 14-plex cytokine panel (TNF-a, IL-4, IL-13, IL-2, GM-CSF, sCD40L, CCL5, CCL3, IL-6, IL-10, IFN-g, VEGF, IL-8, and CCL4." (PMID 40657638, 2025).
COVID-19 (continued). "Residents of EA with COVID-19 and FLS had higher production of IL-12p70, IL-6, IL-1β, IL-2, and IL-1ra compared to residents of NEA, as well as an increased production of IL-10 in COVID-19 patients." (PMID 40165959, 2025). "Multiple studies have confirmed a positive correlation between the severity of COVID-19 and the levels of C-reactive protein (CRP), IL-2, IL-6, IL-7, IL-8, and TNF-α cytokines." (PMID 40371107, 2025). "A significant increase in IL-2, MCP-1, and MIP-1α with CVP#0B was observed in the case of LPS treatment, aging, COVID-19, NASH patients, and so on." (PMID 40432076, 2025). "HLA-A*24:02-positive PBMCs from COVID-19 mRNA vaccine recipients were cultured with T cell activators (CD3/CD28/CD2) and IL-2 for 10 days to expand T cell populations." (PMID 41280906, 2025). "We and others demonstrated that several cytokines and chemokines including IL‐2, IL‐6, IL‐7, IL‐10, IL-15, IL-17, IP‐10, MCP‐1, TNF‐α, GCSF were related to disease severity and mortality in COVID-19." (PMID 40315230, 2025). "At very high exposure level, COVID-19-positive individuals demonstrated a continuous increase in IFN-γ, IL-2, IL-6, and IL-17A, while TNF peaked early and IL-10 showed minimal expression." (PMID 40406109, 2025). "Among others, we investigated the concentration of IL-2 and TNF – cytokines which are some of the best-studied components of the cellular response after vaccination against COVID-19." (PMID 40226625, 2025). "In a double-blind, randomised, placebo-controlled trial involving adults recently diagnosed with COVID-19, four weeks of PEA supplementation led to significant reductions in IL-1β and IL-2 concentrations." (PMID 39062193, 2024). "Compared with age-matched unexposed elderly individuals, convalescent COVID-19 patients presented with more IFN-γ and less IL-7, while IL-2, IL-6, IL-10, IL-12p70, IL-33 and CCL19/MIP-3 were unchanged." (PMID 38424104, 2024). "The levels of IL-2 and IFN-γ were further validated by ELISA, confirming that IFN-γ in COVID-19 convalescent plasma was significantly increased." (PMID 38424104, 2024). "GMCSF, IL-13, IL-1β, IL-2, IL-4, and IL-5 were undetectable in the vast majority of both TTP and COVID-19 samples." (PMID 39337495, 2024). "A significant change in cytokine (including IFN-α, β, and γ; IL-2, IL-6, IL-7, IL-12, and IL-1β) and chemokine (including CCL 2, 3, and 5; CXCL10, CXCL9, and CXCL8) levels in severe COVID-19 cases was also found." (PMID 38255322, 2024). "Other components, such as interleukins (IL-2, IL-6, IL-7, IL-10) and TNF-α are connected to severe COVID-19 symptoms, where cytokine storm (a sudden increase in cytokines) occurs instead of a healthy immune response (Fricke-Galindo and Falfán-Valencia 2021)." (PMID 38240884, 2024). "Overall, our study clarified the interplay between IL-2, TNF-α, IFN-γ, and CRS in patients with COVID-19 and highlighted potential avenues for therapeutic intervention." (PMID 39359733, 2024). "As patients recuperate from COVID-19, cytokine levels including TNF-α, TGF-b, IFN-g, IL-1b, IL-2, and IL-4 subside." (PMID 38844850, 2024). "These molecules modulate CS in COVID-19, notably meloxicam, which exhibited a downregulatory effect on cytokines (IL-6, CCL2, GM-CSF, CXCL10, IL-2, and TNF-α)." (PMID 39518964, 2024). "As reported in our prior study, at 13 months after discharge, 11.6% of the HCWs with severe COVID-19 had elevated IL-6, and more than 98% had normal levels of the remaining five cytokines (IFN-γ, IL-10, IL-2, IL-4 and TNF-α)." (PMID 36908474, 2023). "al. who find IP-10, IL-2, MDC, IL-15 significant at the univariate level for discriminating MIS-C from COVID-19." (PMID 37685502, 2023). "Severe patients (n = 6) showed a significant increase in a subset of plasma cytokine/chemokine levels (IL-2, IL-4, IL-6, IL-8, MIP-1β, and TNF-α; ANOVA, p adjusted <0.05 to <0.001) in comparison with the pauci COVID-19 patients (n = 8) and/or controls." (PMID 37047752, 2023).
COVID-19 (continued). "Mapping relation examination between COVID-19 and Ephedra-Glycyrrhiza exhibited that the key markers were tumor necrosis factor-α (TNF-α), interleukin-2 (IL-2), albumin (ALB), FOS proto-oncogene, and prostaglandin- endoperoxide synthase 2 (PTGS2)." (PMID 37654998, 2023). "Previous reports have associated differential expression of several constituent genes of the IL2-AIS, including CISH, AREG, DUSP2, NFKBIA and TNFAIP3, in COVID-19 patients." (PMID 37700317, 2023). "Through stimulation with the recombinant SARS-CoV-2 S protein in whole blood, we identified a signature for COVID-19 based on the cytokines IFN-γ, IL-2, IP-10, IL-1β, IL-6, IL-8, and TNF." (PMID 37018291, 2023). "Reports from convalescent COVID-19 patients and vaccinated individuals showed that TH1 cytokines (IFN-γ, IL-2) marked the presence of long-lasting, antigen-specific cellular responses." (PMID 37334376, 2023). "The cytokine levels of IL-2, IL-6, IL-7, G-CSF, IP10, MCP1, MIP1A, and TNF-α are determined and were mostly found to be elevated in severe COVID-19 patients with ARDS development related to lung damage and tissue fibrosis." (PMID 36901868, 2023). "By using canonical correlation analysis (CCA), the gut microbiota composition of 30 patients with COVID-19 was visualized by prognostic groups with five serum cytokines – IFN-γ, IL-2, IL-10, TNF-α, and anti-SARS-CoV-2 S immunoglobulin G (IgG) titers." (PMID 37051240, 2023). "Our results showed that COVID-19 patients had significantly higher levels of IFN-γ, TNF, IL-1β, IL-2, IL-6, IL-8, and IP-10 than the unexposed group." (PMID 37018291, 2023). "The frequencies of IFN-γ+, IL-2+, or IFN-γ+IL-2+ T cells were significantly lower for both SOT and controls with mild COVID-19, compared to severe disease, whereas more ambiguous results were obtained for IL-21 producing cells." (PMID 36839516, 2023). "Patients with COVID-19 typically have higher levels of leptin, TNF-∝, interleukin-1, interleukin-2 and interferon-gamma but lower levels of helper T cells, cytotoxic T cells, regulatory T cells and natural killer (NK) cells (IFN-∝)." (PMID 37297724, 2023). "Other differences include a transcriptional signature of IL-2 STAT5 signaling elevated only in DS and a signature of heme metabolism being elevated in DS but repressed in COVID-19." (PMID 37379383, 2023). "The aim of this study was to evaluate a COVID-19 vaccine allergy using in vitro T-cell exposure to the tested drug with the flow cytometry measurement of CD69, CD40L, TNFa, IFNG, IL-2, IL-4, IL-6, IL-10, intracellular granulysin, and IFNgamma." (PMID 37686102, 2023). "The results of 103 elderly patients showed that age, IL-2, IgG Sum/IgG 1, DD, LY #, NLR, and PDW were considered to be relevant factors affecting the severe degree of COVID-19." (PMID 38106427, 2023). "Altogether, eight biomarkers stood out as the main inflammatory mediators with discriminative potential between the COVID-19 (recovered/long-COVID-19) and healthy unexposed groups: IFN-γ, IL-10, IL-6, IL-2, IP-10, TNF, IL- 1β, and IL-8." (PMID 37018291, 2023). "Among critically ill patients with COVID-19, serum IL-6 and IL-10 levels are usually higher, while serum GM-CSF, TNF- α, IFN-γ, IL-2 and IL-8 serve as ancillary cytokines with clinical prognostic value in contrast to patients without critical disease." (PMID 37568402, 2023). "For example, in contrast to the transcriptional changes induced by low-dose IL-2 in T1D patients, we observed a downregulation of CISH and an upregulation of AREG in COVID-19 patients during acute infection, across multiple immune cell types." (PMID 37700317, 2023). "In response to SARS-CoV-2 S-RBD and SARS-CoV-2 ICL, we observed significantly increased frequencies of CD8+ T cells expressing IFN-γ, IL-2, TNF-α, and IL-17A in MIS-C compared to children with COVID-19 and other infectious diseases." (PMID 38116577, 2023).
COVID-19 (continued). "Early into the pandemic, those diagnosed with COVID-19 were found to display significantly elevated proinflammatory responses, including increased levels of IL-6, TNF, IL-2, IL-1β, IP-10, IFNγ, MCP1 and MIP1α." (PMID 37091818, 2023). "Various cytokines (IFN-γ, IL-1β, IL-6, IL-2, and TNF-α) had altered levels in COVID-19, and the cytokine storms correlate with the severity and progression of COVID-19." (PMID 37565145, 2023). "Interestingly, we found that IFN-I signaling in COVID-19 patients is highly correlated with immune-activating cytokine signaling pathways such as IL-2, IL-16, and IL-17, which could provide novel insights on the coregulatory relationship of IFN-I with other effector cytokines." (PMID 36992700, 2023). "The COVID-19 group had significantly higher levels of IFN-γ (P<0.01), IL-2 (P<0.01), IP-10 (P<0.01), IL-1β (P = 0.001), IL-6 (P = 0.002), IL-8 (P = 0.003), and TNF (P = 0.014) when compared to the unexposed healthy group." (PMID 37018291, 2023). "The RS between activation marker concentrations and the severity of COVID-19 are calculated by training data set Z2KP, where the activation markers are IL-17a, IL-2, GATA3, IFN-γ, IL-4, IL-10, PD_1, CD40L, RORγt, CTLA_4, CCR7, TNF-α and IL-6, respectively." (PMID 36845115, 2023). "The production of cytokines in COVID-19 patients and CD4+ T lymphocytes isolated from SARS-CoV-2-vaccinated subjects stimulated with a peptide pool predominantly expressed IL-2 and IFN-γ, whereas IL-17A, IL-4, and IL-10 were less frequent and not significant." (PMID 38140191, 2023). "During COVID-19 progression, abnormal levels of IL-1β, TNF-α, IL-2, IL-7, IL-12, macrophage colony-stimulating factor (M-CSF), granulocyte colony-stimulating factor (G-CSF), and others can be detected in patient’s blood." (PMID 36702907, 2023). "In response to SARS-CoV-2 S-RBD and SARS-CoV-2 ICL, we observed significantly increased frequencies of CD4+ T cells expressing IFN-γ, IL-2, and IL-17A in MIS-C compared to children with COVID-19 and other infectious diseases." (PMID 38116577, 2023). "The activation of T cells and their ability to produce large amounts of effector cytokines (IL-2, IFNγ, and TNF) was also reflected by EVs obtained from COVID-19 patients with severe disease in the current study." (PMID 36982991, 2023). "Interestingly, recent improvements in the pathophysiologic understanding of COVID-19 revealed that the severity of COVID-19 is strongly associated with cytokine release syndrome (CRS), which is characterized by elevated tumor necrosis factor (TNF-α), interleukin (IL)-6, IL-2, IL-7, and IL-10." (PMID 36770606, 2023). "At baseline, there were significantly increased frequencies of CD4+ T cells expressing IFN-γ IL-2, TNF-α, and IL-17A in MIS-C compared with children with COVID-19 or with other infectious diseases." (PMID 38116577, 2023). "Previously, our group has shown an increased level of cytokines in the antigen-specific culture supernatants including IFNγ, IL-2, IL-4, IL-13, and IL-17 in MIS-C in comparison with acute COVID-19 and other infectious diseases." (PMID 38116577, 2023). "A significant increase in 40 analytes was identified, including IL-1, IL-2, IL-6, IL-10, IFN-γ, and TNF-α, which are important proinflammatory cytokines that have been established in patients with COVID-19." (PMID 36290634, 2022). "Higher plasma levels of proinflammatory cytokines such as IL-1, IL-2, TNF-α, GM-CSF, and MCP1 have been reported in COVID-19 patients." (PMID 35687545, 2022). "MMP-7, TGF-β, CCL2, CCL-3, CXCL-10, G-CSF, IFN gamma, IL-10, IL-2, IL-4, IL-6, IL-7, TNF-α, IL-6, and IGF-1 were studied for their correlation to lung involvement in COVID-19 patients." (PMID 36286038, 2022). "Particularly, monocytes from patients with acute COVID-19 secreted reduced G-CSF, MIP-1α, MIP-1β, MCP-1, TNF-α and IL-2 levels upon bacterial challenge." (PMID 35007290, 2022).
COVID-19 (continued). "Our findings confirm and extend previous study results showing that SARS-CoV-2-specific IL-2 and/or IFN-γ-producing cells were present in blood samples from recovered individuals who had milder COVID-19 courses." (PMID 35693828, 2022). "On the other hand, serum levels of cytokines in COVID-19 ICU patients showed a significant increase in the production of GM-CSF, IFN-α, IL-2, IL-4, and IL-6 and a significant decrease in the levels of IFN-γ, IL-5, IL-12, IL-17A, and TNF-α." (PMID 36363785, 2022). "Increased plasma levels of pro-inflammatory cytokines and chemokines (especially IL-2, IL-6, IL-10, and TNF-α) with impaired IFN-I activation in severe COVID-19." (PMID 36072602, 2022). "Plasma levels of IL-2, IL-7, TNF-α, and other pro-inflammatory cytokines were elevated in COVID-19 patients, and levels of various inflammatory cytokines were higher in (ICU) patients than in non-ICU patients." (PMID 36299906, 2022). "COVID-19 moderate patients, compared to HD, also presented a high percentage of IFN-γ+IL-2+TNF+ and IL-2+TNF+." (PMID 35887351, 2022). "Nevertheless, we did not observe this expected behavior in participants developing severe COVID-19 after SARS-CoV-2 infection, whose helper T cells exhibited similar IL-2 and IFN-gamma expression patterns independently of expressing or not PD-1." (PMID 35860236, 2022). "Nevertheless, increased expression of NKG2A led to the reduced levels of CD107a (degranulation marker), IFN-γ, IL-2, granzyme B, and TNF-α in NK cells from COVID-19 patients." (PMID 36505489, 2022). "Meanwhile, elevated levels of serum IL-2, TNF-α, IL-7, granulocyte colony-stimulating factor, and interferon-gamma-induced protein 10 were correlated with the severity of COVID-19." (PMID 36299906, 2022). "On the other hand, higher mean levels of IL-2 (p < 0.001) and IL-5 (p < 0.01) were produced by PHA-stimulated PBMCs from COVID-19 ICU patients compared to HC." (PMID 36363785, 2022). "A controversial role is played in COVID-19 by CD8+ T cells with reduced levels of CD107a, IFN-γ, IL-2, and granzyme B compared to healthy cells, or by CD8+ T cells with increased production of granzyme A and B and perforin during COVID-19." (PMID 36359755, 2022). "IL-6, IL-5, GCSF, IL-2, TNF-α, GMCSF, and IFN-γ were identified as COVID-19-related distinguishable cytokines, but only one (IL-12p70) was detected in the noninfected people." (PMID 35967091, 2022). "From this search, we identified 6 cytokines that are critically involved in the pathogenesis of COVID-19 induced ARDS lung injury (IL-1β, IL-2, IL-6, IL-8, IL-10, and TNFα)." (PMID 35033181, 2022). "We first observed a significantly elevated level of 7 serum cytokines (IL-1Ra, IL-2, IL-3, IL-10, IL-12p40, CXCL10, and HGF) in all COVID-19 cases when compared with controls." (PMID 35386707, 2022). "Decreased production of CD107a+, IFN-γ+, IL-2+, and granzyme B+ was also described in CD8+ T lymphocytes in COVID-19." (PMID 36359755, 2022). "Our results demonstrate that melatonin consumption for 14 days significantly decreases plasma levels of IL-4, IL-2, IL-1β, IFN-γ, and IL-6 in COVID-19 patients." (PMID 36254292, 2022). "The gene expression profile of activated lung macrophages in COVID-19 displays similarity with sHLH and MAS macrophages, and both sHLH/MAS and SARS-CoV-2 – induced cytokine storms include IL-2, IL-7, G-CSF, IP-10, MCP-1, MIP-1α and 1β, and TNF-α elevations." (PMID 35401519, 2022). "Of the 16 mediators elevated in early COVID-19 compared with healthy controls, 11 decreased over time (CCL3, CCL4, TNF-α, IL-6, CCL13, IL-4, IFN-α2a, CXCL10, CXCL11, IL-2, and IL-12)." (PMID 35397798, 2022). "Many investigations have reported high levels of pro-inflammatory cytokines and chemokines, including IL-2, IL-6, IL-10, IFN-γ, CXCL10, and CCL2 in COVID-19." (PMID 35664675, 2022).